CXCL5 (C-X-C motif chemokine ligand 5)
Description:
Involved in neutrophil activation. In vitro, ENA-78(8-78) and ENA-78(9-78) show a threefold higher chemotactic activity for neutrophil granulocytes.
Synonyms: SCYB5; ENA-78
Tractability: Antibody: its Gene Ontology location is reachable by antibodies, with high confidence; UniProt places it where antibodies can reach, with medium confidence; UniProt predicts a signal peptide or a membrane-spanning region.
Gene: Protein-coding gene on chromosome 4 (73,995,642 to 73,998,677, reverse strand). Ensembl gene ENSG00000163735.
Subcellular location: Secreted
Subcellular location (Human Protein Atlas): Vesicles; Predicted to be secreted
Pathways (Reactome):
Signal Transduction: Chemokine receptors bind chemokines; G alpha (i) signalling events
Gene Ontology:
Molecular function: identical protein binding; protein binding; chemokine activity; CXCR chemokine receptor binding
Biological process: antimicrobial humoral immune response mediated by antimicrobial peptide; cell-cell signaling; cellular response to lipopolysaccharide; chemotaxis; inflammatory response; neutrophil chemotaxis; positive regulation of cell population proliferation; signal transduction; defense response; immune response
Cellular component: extracellular region
Genetic constraint (gnomAD): Loss-of-function variants: 10 observed, 11.53 expected, observed/expected ratio (o/e) 0.87, 90% interval 0.53 to 1.47. The upper end of that interval is the gene's LOEUF score, 1.47, which puts it in group 6 of 6, group 1 being the genes least tolerant of losing a copy. Missense variants: 153 observed, 141.15 expected, observed/expected ratio (o/e) 1.08, 90% interval 0.95 to 1.24. Synonymous variants: 66 observed, 56.2 expected, observed/expected ratio (o/e) 1.17, 90% interval 0.96 to 1.44.
Homologues: Orthologues: chimpanzee CXCL5 (97% identical), macaque CXCL5 (82% identical), rabbit CXCL5 (75% identical). Paralogues in human: CXCL6 (80% identical), PPBP (43% identical), CXCL1 (41% identical), CXCL2 (41% identical), CXCL3 (40% identical), PF4 (34% identical), PF4V1 (32% identical), CXCL9 (29% identical), CXCL8 (27% identical), CXCL13 (22% identical), CXCL10 (19% identical), CXCL11 (19% identical).
Diseases named in the same sentence as CXCL5 in open-access papers:
CXCL5 is named in the same sentence as 329 diseases in open-access papers, as found by Europe PMC text mining. Sharing a sentence is not in itself a finding about the gene and the disease. The quoted sentences say what the papers report.
breast carcinoma (74 papers, 2013 to 2025). "CXCL5 has been implicated in promoting breast cancer metastasis by enhancing the pro-inflammatory environment within the TME and by stimulating angiogenesis." (PMID 40486614, 2025). "In PyMT-induced mammary tumorigenesis, deletion of TβRII was associated with a strong increase in secretion of CXCL1 and CXCL5 chemokines from mammary carcinoma cells and significantly correlated with increased tumor progression and metastasis formation." (PMID 25280532, 2014). "Notably, CXCL5 and CCL19 were 2 chemokines found to be highly expressed in MVI, with CXCL5 having previous associations with metastasis in colorectal cancer and breast cancer." (PMID 39670859, 2025). "Notably, the serum levels of S100A14, CCL2/CXCL5 have significant diagnostic value for discerning breast cancer patients from healthy individuals." (PMID 32483412, 2020). "Among premenopausal AA women, one SNP (rs425535) in chemokine (C-X-C motif) ligand 5 (CXCL5) was observed to be inversely associated with breast cancer risk (P-trend for the A allele= 0.006), with AG/AA genotypes associated with a 39% reduced risk compared to the GG genotype." (PMID 23991131, 2013). "Importantly, S100A14 expression is highly associated with CCL2 and CXCL5 expression in breast cancer tissue and serum samples, supporting our hypothesis that S100A14 regulates CCL2/CXCL5 expression in a physiological context." (PMID 32483412, 2020). "Increased expression of CXCL5 in breast cancer patients correlates with poor prognosis, highlighting its role in facilitating tumor progression." (PMID 40486614, 2025). "Previous studies have shown that the CXCL5 expression is elevated in multiple types of cancer, including colorectal cancer, breast cancer, gastric cancer, bladder cancer, and hepatocellular carcinoma." (PMID 40313933, 2025). "High DDR1 expression correlated with poor prognosis in breast cancer patients, and increased CXCL5 expression correlated with an increased number of malignant phenotypes of breast cancer cells." (PMID 40391215, 2025). "CXCL5 was reported to be involved in the formation of a premetastatic niche promoting breast cancer cells to proliferate and colonize in the bone." (PMID 38281962, 2024). "In patients with periodontitis, gingival disease facilitates lymph node metastasis, particularly in breast cancer, which is associated with increased expression of CCL5, CCL2, and CXCL5." (PMID 38139161, 2023). "Studies using data from the Oncomine database showed significantly lower CXCL5 mRNA expression in breast cancer tissue than in healthy breast tissue (p < 0.05)." (PMID 37370728, 2023). "Overexpression of CXCL5 in TNBC compared to ER+ subtypes was also noted in molecular subtype analyses of breast cancer." (PMID 37370728, 2023). "We propose that this is due to the secretion of multiple cytokines that have been shown to increase breast cancer aggressiveness, namely CXCL5, COX-2, MMP-9, and IL-6." (PMID 37760470, 2023). "Another breast cancer study recently revealed that collagen-induced DDR1 upregulated CXCL5, which promoted the formation of NETs and enhanced Treg infiltration, thereby facilitating the growth and metastasis of breast cancer." (PMID 38136314, 2023). "Together, these data suggest that the induced secretion of CXCL5 in the co-culture system played a critical role in promoting breast cancer cell malignancy." (PMID 36104403, 2022). "CXCL5 was identified by Romero-Moreno and colleagues as a key factor in breast cancer cell colonization of the bone in the mouse model." (PMID 35454913, 2022). "We also examined the serum levels of resistin and CXCL5 in breast cancer patients by ELISA, and the results showed a positive correlation between the two proteins." (PMID 36104403, 2022). "The orthotopic xenograft in mice by breast cancer cells after co-culture with R-ADSCs had a larger tumor growth and more CXCL5 expression than control." (PMID 36104403, 2022).
breast carcinoma (continued). "Recently, the CXCL5/CXCR2 axis is sufficient to promote breast cancer colonization during bone metastasis." (PMID 33869023, 2021). "Endogenous Pparγ1 induced expression of both an EphA2-Amphiregulin and an inflammatory INFγ and Cxcl5 signaling module, that was recapitulated in human breast cancer." (PMID 33946495, 2021). "As tumor-promoting proteins that are expected to be downregulated in osteocyte-derived CM, we focused on the expression levels of CXCL1, and CXCL5, two chemokines that are involved in the migration of breast cancer cells." (PMID 33802279, 2021). "CXCL5 can promote the proliferation of breast cancer DTCs and its colonization in bone, in turn, blockade of CXCR2, the receptor of CXCL5, leads to DTCs dormancy." (PMID 35006432, 2021). "An ex vivo tumor/bone co-culture model was used to demonstrate that the CXCL5/CXCR2 axis is sufficient to promote breast cancer colonization during bone metastasis." (PMID 34831167, 2021). "Pparγ1+/+ ErbB2 mammary tumors showed increased expression of specific chemokines and cytokines (Cxcl5, Cxcl19, Cxcl13, IL1b and Tnfrsf13c)." (PMID 33946495, 2021). "In summary, our results identify a S100A14- NF-κB -CCL2/CXCL5 signaling axis in promoting breast cancer metastasis." (PMID 32483412, 2020). "Recent evidence suggests that CXCL5 promotes bone metastasis in breast cancer via the ERK/MSK1/Elk-1/Snail signalling pathway." (PMID 32415115, 2020). "Analysis of published datasets found that the coexpression of S100A14 and CCL2/CXCL5 in breast cancer tissues is a significant determinant of poor metastasis-free survival for breast cancer patients." (PMID 32483412, 2020). "Collectively, we identify S100A14 as an upstream regulator of CCL2/CXCL5 signaling and a metastatic driver of breast cancer." (PMID 32483412, 2020). "It has been recently proposed that a FOSL1 signature including TAN-attracting CKs (CXCL8, CXCL6 and CXCL5) is activated in Basal B type breast cancer cell lines." (PMID 31991796, 2020). "Bone marrow-derived mesenchymal stem cells (MSCs) express CXCL1 and CXCL5 to recruit PyMT breast cancer cells and prompt the migration in a CXCR2-dependent manner in vitro." (PMID 31788042, 2019). "In breast cancer models, IL17 is found to increase the secretion of CXCL1 and CXCL5 by mammary carcinoma cells, which further facilitates cancer progression." (PMID 31010242, 2019). "The chemokines that participate in the migration of MDSCs in breast cancer include CXCL5, CCL1 and CCL2 (also known as monocyte chemotactic protein-1 (MCP-1)) and CCL5." (PMID 27542274, 2016). "For example, in breast cancer, ENA-78/CXCL5 promotes breast cancer cell migration and invasion, and is reported to stimulate cancer stem cell (CSC) activity." (PMID 26361584, 2015). "It has been shown that TGF-β inhibited TNF-α-induced CXCL1 release in human ECs and TGF-β regulated suppression of inflammatory genes such as CXCL1 and CXCL5 in mammary carcinoma cells." (PMID 23665907, 2013). "Besides, in breast cancer, the CXCL5/CXCR2 axis promotes tumor cell proliferation and colonization in bone." (PMID 40313933, 2025). "Additionally, by examining the protein’s tissue expression by IHC staining, CXCL5 protein expression was significantly higher in breast cancer tissues than in tissues of healthy controls (p < 0.05)." (PMID 37370728, 2023). "In addition, the secretion of CXCL1 and CXCL5, two cytokines involved in breast cancer metastasis, was moderately increased in all subgroups after indirect co-culture with MDA-MB-231 cells." (PMID 36710348, 2023). "In addition, CXCL5‐neutralizing antibody‐treated mice showed reduced metastasis of breast cancer cells, mainly through inhibition of ERK/Snail signaling." (PMID 35702353, 2022). "In addition, CXCL5 secreted by healthy donor-derived ADSCs showed an enhancing effect on breast cancer cell proliferation." (PMID 36104403, 2022).
breast carcinoma (continued). "These newly discovered pathways of resistin may be mediated through ADSCs in the breast tumor microenvironment via CXCL5 secretion, leading to the malignant behaviors of breast cancer cells." (PMID 36104403, 2022). "These clinical data and our preclinical findings together suggest the potential of CXCL5 secretion induced by resistin-stimulated ADSCs in the breast tumor microenvironment, and that promoted breast cancer cell malignancy with the participation of ERK signaling pathway." (PMID 36104403, 2022). "CXCL5-mediated ERK/Snail signaling increased the potential of metastases in breast cancer." (PMID 36151545, 2022). "Breast cancer cells treated with the recombinant proteins of CXCL5 showed similarly enhanced cell migration and invasion ability as occurred in the co-culture model, whereas application of neutralizing antibodies against CXCL5 reversed these phenomena." (PMID 36104403, 2022). "In addition, clinical analysis revealed a positive correlation between the expression of resistin and CXCL5 in both tumor tissues and serum specimens of breast cancer patients." (PMID 36104403, 2022). "There is also possibility that CXCL5 may be co-released by breast cancer cells as an autocrine or paracrine factor to promote malignancy in our transwell co-culture model." (PMID 36104403, 2022). "The current study suggests that resistin-stimulated ADSCs may interact with breast cancer cells in the tumor microenvironment via CXCL5 secretion, leading to breast cancer cell malignancy." (PMID 36104403, 2022). "CXCL5 neutralizing antibodies treatment decreased the metastatic rate of breast cancer cells." (PMID 34439836, 2021). "Similarly, TCGA data analysis revealed elevated expression patterns of CXCL8, CXCL1, and CXCL5 in ER- breast cancer specimens." (PMID 33912188, 2021). "Furthermore, CXCR2 and several of its ligands (CXCL1, CXCL2, CXCL5, CXCL7 and CXCL8) have also been linked to breast cancer progression and metastatic invasion." (PMID 32581213, 2020). "We further examined whether the S100A14-CCL2/CXCL5 axis can serve as a predictor of the prognosis for patients with breast cancer." (PMID 32483412, 2020). "Thus, we detected the serum levels of S100A14, CCL2 and CXCL5 in our prospective cohort of 150 breast cancer patients and 125 healthy controls." (PMID 32483412, 2020). "Moreover, ERK activation was associated with the effects of CXCL5, another chemokine, on the downregulation of E-cadherin in MDA-MB-231 and MCF-7 breast cancer cells." (PMID 33374849, 2020). "Indeed, the GEO database analysis demonstrated that the increased expression of S100A14, CCL2 or CXCL5 in primary breast cancer was a determinant of poor metastasis-free survival in patients." (PMID 32483412, 2020). "One study revealed that the Kruppel-like factor KLF4, a transcription factor, could induce GM-CSF production via CXCL5 to modulate the maintenance of MDSCs in breast cancer." (PMID 27542274, 2016). "However, up-expression of CXCL5 was also found in malignant tumours, such as breast cancer, nasopharyngeal cancer and also HCC, and closely correlated with poor prognosis 31–33." (PMID 24268047, 2014). "In our study, the CXCL5-rs425535 variant A allele was associated with a decreased risk of breast cancer in AA premenopausal women, but not EAs, and was much more common among AA (MAF= 39.7%) than among EA women (MAF=13.5%)." (PMID 23991131, 2013). "Using ex-vivo co-culture systems of breast cancer cells and mouse bones, others have also shown that a CXCL5/CXCR2 (the IL-8 receptor-β) signaling axis might be involved in regulating the balance between cancer cell quiescence/dormancy and subsequent breast cancer outgrowth in bone." (PMID 33809315, 2021).
breast carcinoma (continued). "To further confirm whether CCL2 and CXCL5 function as pivotal chemokines mediating S100A14-induced breast cancer metastasis in vivo, we used the 4T1 orthotopic transplantation model in which mice were treated with CCL2- and CXCL5-neutralizing antibodies or IgG control antibodies." (PMID 32483412, 2020). "Among premenopausal AA women, comparing variant allele carriers to non-carriers, reduced breast cancer risk was associated with CXCL5-rs425535 (OR=0.61, P=0.02), while among EA women, there were associations with TNFA-rs1799724 (OR =2.31, P =0.002) and CRP-rs1205 (OR=0.54, P=0.01)." (PMID 23991131, 2013). "In breast cancer, IL-17 has been shown to stimulate the production of several neutrophil-attracting chemokines, such as CXCL1, CXCL5, and CXCL8." (PMID 40486614, 2025). "Because we previously reported that CXCL5, CCL2, CCL3, and CCL5 occur at low levels in CM collected from aggressive breast cancer cell lines, here we focused on other abundantly secreted chemokines." (PMID 40833805, 2025). "CXCL5 within the TME is primarily produced by tumor cells in specific cancers like HCC, breast cancer, and ICC." (PMID 39670859, 2025). "Neutrophil infiltration had a direct relationship with the expression of IL1R1, IL1RN, IL1RAP, IL6ST, CXCL3, CXCL5, and CXCL6 in most of the subtypes of the breast cancer patients analyzed." (PMID 39201290, 2024). "Only changes in five analytes (CXCL5, CXCL1, CCL17, CXCL10, and IL-6) were seen to overlap across all four breast cancer cell-line EV-stimulated conditions." (PMID 37441083, 2023). "This article summarizes existing knowledge about the roles of CXCL ELR-positive chemokines CXCL1, CXCL2, CXCL3, CXCL5, CXCL6, CXCL7, and CXCL8 as peripheral blood and tissue markers in the diagnosis and prognosis of women with breast cancer." (PMID 37370728, 2023). "Cochrane’s Q test did not provide evidence of heterogeneity between CCL1 (p = 0.227), CCL2 (p = 0.982), CCL18 (p = 0.221), CXCL5 (p = 0.533), CXCL12 (p = 0.977), and CXCL13 (p = 0.520) and breast cancer." (PMID 38075694, 2023). "Once cancer cells metastasize to the bone, different chemokine motif ligands (CXCL12, CXCR4, CXCL5, CXCR2) promote breast cancer cell colonization within the bone." (PMID 36674719, 2023). "Screening by proteome arrays revealed that C-X-C motif chemokine ligand 5 (CXCL5) was released in the conditioned medium of the co-culture system, and phosphorylated ERK was increased in breast cancer cells after co-culture with R-ADSCs." (PMID 36104403, 2022). "With respect to the seven measured chemokines, CXCL5 and CCL23 were substantially decreased in the group of breast cancer patients, while those of CX3CL1 (fractalkine) and CCL5, were significantly elevated." (PMID 35677046, 2022). "Our clinical analyses further support this view, with evidence to show a mutual correlation between the expression of resistin, CXCL5, and ERK phosphorylation in the tumor tissues of breast cancer patients." (PMID 36104403, 2022). "In another model of murine breast cancer, MMTV−Neu (Mouse Mammary Tumor Virus—Neu oncogene), we observed an increase of Cxcl1, Cxcl2, Cxcl3, and Cxcl5 levels in the tumor of MMTV−Neu animals compared to the mammary gland of WT animals." (PMID 34070438, 2021). "Mechanistic studies demonstrated that S100A14 promotes breast cancer metastasis by upregulating the expression and secretion of CCL2 and CXCL5 via NF-κB mediated transcription." (PMID 32483412, 2020). "In breast cancer, based on the tumor type, MDSCs are recruited to the tumor sites by various chemokines including CCL2, CXCL5, and CXCL12 (SDF-1)." (PMID 32726950, 2020). "In breast cancer, the SDF-1/CXCR4 and CXCL5/CXCR2 axes recruit Gr-1+CD11b+ myeloid cells, activate MMP, and upregulate TGF-β1, which contributes to metastasis in mouse models injected with a breast cancer cell line (4T1)." (PMID 32726950, 2020).